BRAF (B-Raf proto-oncogene, serine/threonine kinase)
Diseases named in the same sentence as BRAF in open-access papers (continued):
Sharing a sentence is not in itself a finding about the gene and the disease.
melanoma (continued). "In melanoma, combinations of BRAF and MEK inhibitors are recommended in patients with BRAF-mutated tumours." (PMID 41463281, 2025). "La mutación BRAF V600E es una de las alteraciones genéticas más relevantes en oncología de precisión, comúnmente encontrada en varios tipos de cánceres como el melanoma, el cáncer colorrectal y cáncer de tiroides entre otros." (PMID 40977817, 2025). "BRAF and MEK in combination have proven to work well in BRAF‐mutated melanomas, but because of the low frequency of mutation among ALM, it has limited efficacy in this subtype." (PMID 39415471, 2025). "Adults with locally advanced, unresectable or metastatic BRAFV600-mutant melanoma who were BRAF inhibitor/MEK inhibitor (BRAFi/MEKi) treatment–naïve or pretreated received encorafenib plus binimetinib (part I/run-in)." (PMID 40106536, 2025). "Vemurafenib is a BRAF (rapidly accelerated fibrosarcoma B-type)-targeted therapy used to treat patients with advanced, unresectable melanoma." (PMID 40141318, 2025). "BRAFV600E melanoma resistant to BRAF and MEK inhibitors exhibited increased levels of reactive oxygen species (ROS), which drive MAPK-signaling reactivation." (PMID 39935431, 2025). "Under BRAF inhibition, melanoma cells upregulate glutaminase and transaminases to maintain anaplerosis, enabling survival despite reduced glycolytic input." (PMID 41463281, 2025). "Since mitochondria are the primary source of ROS in cancer cells, mitochondria-targeted antioxidants were tested in mouse models of BRAF-driven melanoma and KRAS-driven lung cancer." (PMID 40646353, 2025). "A phase I/II trial of dabrafenib + trametinib + hydroxychloroquine in patients with BRAF-mutant melanoma demonstrated promising response rates in a treatment refractory patient population, but did not meet the pre-specified 1 year PFS rate of 60%." (PMID 40457397, 2025). "Then, melanoma eludes BRAF V600E targeting by the reactivation of alternative survival pathways through RTK or MAPK pathway reactivation mediated by activated RAS." (PMID 40872623, 2025). "A 71-year-old male with stage IV melanoma (BRAF wild-type) and lung metastases received one cycle of adjuvant pembrolizumab, followed by four cycles of ipilimumab/nivolumab." (PMID 40751168, 2025). "In routine clinical practice, vemurafenib has significantly reshaped treatment expectations for patients with advanced BRAF-mutant melanoma." (PMID 41302945, 2025). "Given the success of BRAF inhibitors in melanoma and other malignancies, establishing a model for BRAF-driven MPNST is crucial for evaluating targeted treatment strategies." (PMID 41063628, 2025). "Ferroptosis has demonstrated significant potential in overcoming therapy resistance in melanoma, including resistance to BRAF inhibitors and immunotherapy." (PMID 41235238, 2025). "BRAF and NRAS gene mutations occur at an early point in melanoma pathogenesis and are consistently sustained during further tumor progression, taking part in the pathogenesis of invasive melanoma but also in cooperation with other mutations." (PMID 41049012, 2025). "Mutation of BRAF and NRAS and overexpression of PGC-1α in melanoma cells indicate high OXPHOS and a greater dependency of these cells on glycolysis." (PMID 40404919, 2025). "Further, a subset of individuals with NF1 wild-type MPNST (3-12% depending on the study) have been reported to harbor BRAF mutations, among which BRAFV600E is the most frequent, similar to observations in melanoma and additional epithelial cancers." (PMID 41063628, 2025). "New treatment approaches are warranted for patients with advanced melanoma refractory to immune checkpoint blockade (ICB) or BRAF-targeted therapy." (PMID 39753970, 2025). "The E3 ligase TRIM63 demonstrates a robust correlation with melanoma malignancy, particularly in cases involving BRAF mutants." (PMID 41315179, 2025).
melanoma (continued). "A prospective, single-center non-randomized study explored the efficacy of neoadjuvant targeted therapy for patients with borderline resectable BRAF-mutant IIIB-IV melanoma." (PMID 40857557, 2025). "The molecular and mechanistic link between GPD1-ELOVL6 with BRAF V600E in melanoma is yet to be established." (PMID 39795195, 2025). "The VE-BASKET trial assessed vemurafenib in various non-melanoma BRAF V600E mutant tumors, including gliomas, showing a 25% ORR with a median PFS of 5.5 months and a median OS of 28.2 months in the overall population." (PMID 40332392, 2025). "In the last 10 years, the treatment of melanomas improved with the adoption of monoclonal antibodies use, such as Ipilimumab and Pembrolizumab (both PD-1 inhibitors), BRAF inhibitors Dabrafenib and Vemurafenib and Trametinib (MEK inhibitor)." (PMID 40868208, 2025). "This study highlights the distinct epidemiological and clinical characteristics of Japanese melanoma patients, with a predominance of ALM and MCM and lower BRAF mutation rates." (PMID 40192945, 2025). "The most striking results of our study were that BRAF and NRAS mutated melanomas were significantly associated with conventional poor prognostic variables than WT melanomas, such as ulceration, higher mitotic rate, NM histotype, and AHM subtype." (PMID 40867317, 2025). "Following BRAF and MEK inhibition (BRAFi + MEKi) treatment in BRAF mutant melanoma, the MAPK signaling pathway translocates into the ER via an SEC61-dependent mechanism." (PMID 40655947, 2025). "The most common BRAF mutations, BRAFV600E/K, are found in melanoma, hairy cell leukaemia, thyroid cancer and colorectal cancer and can signal as constitutively active monomers to drive MEK1/2-ERK1/2 activation and disease progression." (PMID 41249187, 2025). "The GPA score for melanoma incorporates KPS, age, presence of extracranial metastases (ECM), number of brain metastases, and BRAF mutation status." (PMID 41296115, 2025). "The HDAC1-3 inhibitor entinostat, in combination with BRAF/MEK inhibitors, synergistically increased apoptosis induction in BRAF-mutant melanoma cells, thus killing cells that would have survived BRAF/MEK inhibitors alone." (PMID 39935431, 2025). "BRAF inhibitors are small molecule drugs that inhibit mutant BRAF kinase in the MAPK pathway, causing tumor regression in melanoma." (PMID 40981345, 2025). "Activating BRAF mutations drive MAPK pathway signaling (RAF–MEK1/MEK2–ERK1/ERK2), resulting in melanoma development and progression." (PMID 40106536, 2025). "Los BRAFis como vemurafenib y dabrafenib, son altamente efectivos en el melanoma avanzado positivo para BRAF V600E, con una tasa de respuesta de aproximadamente 60–80 %." (PMID 40977817, 2025). "A systematic review of 91 patients with sarcoid-like reactions during treatment with immune checkpoint inhibitors or BRAF/MEK inhibitors for melanoma found that three developed hypercalcemia." (PMID 40689241, 2025). "Approximately 35–50% of BRAF-mutant and wild-type melanoma cell lines as well as melanoma patients exhibit high oxidative phosphorylation activity." (PMID 40404919, 2025). "In a phase I trial, BRAF-wildtype melanoma patients were treated with a combination of the AKT inhibitor uprosertib and trametinib." (PMID 40399946, 2025). "We confirmed that both BRAF mutant and wild-type melanomas had significantly higher levels compared to normal tissue." (PMID 41155168, 2025). "Tier IA predictors were identified in two cases of melanoma and low-grade spindle-cell sarcoma (BRAF p.V600E, three patients) and plexiform neurofibroma (NF1 aberrations, two patients)." (PMID 41373618, 2025). "Combination ipilimumab and nivolumab resulted in progression-free survival (PFS) of 11.2 months in patients with BRAF mutant melanoma compared to 11.7 months in BRAF wild-type tumours." (PMID 40362630, 2025).
melanoma (continued). "The depletion of DUSP4 induce oncogene overdose in both drug-naïve and drug-resistant BRAF-mutant melanoma cell lines through the hyperactivation of MAPK signaling." (PMID 40141318, 2025). "Our previous studies highlighted the potential utility of combined BRAF/Src inhibition for preventing the emergence of Rac-driven BRAFi/MEKi-resistance in undifferentiated melanoma cell lines." (PMID 41109929, 2025). "A prospective, multicentric, phase 2 clinical trial was conducted to test a combination treatment with encorafenib (BRAFinhibitor) and binimetinib (MEK inhibitor) followed by radiotherapy in patients with BRAF V600-positive melanoma and brain metastases." (PMID 40977811, 2025). "For example, the siRNA-mediated knockdown of ATOX1 in wild-type BRAF melanoma cells significantly diminished the accumulation of copper ions and reduced the susceptibility of cells to combination therapy with trametinib and disulfiram." (PMID 40721800, 2025). "In BRAF V600-mutant melanoma, the addition of the MEK inhibitor cobimetinib to the BRAF inhibitor vemurafenib increased the ORR from 45% to 68%." (PMID 40869045, 2025). "Some studies have described specific dermoscopic patterns in BRAF-mutant melanomas compared with those in BRAFWT melanomas." (PMID 41010758, 2025). "This national cohort study presents the largest dataset on melanoma BRAF biomarker status published to date, with 13 138 BRAF-tested tumours registered." (PMID 40902091, 2025). "Though BRAF inhibitors were initially impactful for melanoma, resistance, particularly to vemurafenib, eventually emerged, facilitated by secondary mutations reactivating the MAPK pathway." (PMID 40510029, 2025). "Compared to dabrafenib, a clinically approved BRAF inhibitor, HT exhibited comparable anti-proliferative and anti-invasive effects in C32 melanoma spheroids." (PMID 40725203, 2025). "In melanoma, triplet regimens combining BRAF/MEK inhibitors with ICIs have improved progression-free survival and response durability compared with targeted therapy alone." (PMID 41291343, 2025). "Vemurafenib, a medication primarily used to treat melanoma, has also demonstrated effectiveness when administered alone to treat NSCLC with BRAF mutations." (PMID 40729346, 2025). "In this study, plasma-derived levels of ctDNA from assays for BRAF and NRAS driver mutations as well as TERT promotor mutations were analyzed in patients with advanced melanoma." (PMID 40002300, 2025). "Resistance to current frontline treatments, such as BRAF inhibitors (BRAFi), remains a major obstacle in melanoma treatment." (PMID 40386826, 2025). "Both experienced benefits, but with a notably more synergistic and narrow dosage range for NRAS mutant melanoma (mean Bliss score of 0.27 in NRAS vs. 0.1 in BRAF mutants)." (PMID 39199684, 2024). "The area percentage of LOXL3 was significantly higher in dysplastic nevus compared to BRAF+ (p = 0.0061) and BRAF− melanoma (p = 0.0270)." (PMID 39273022, 2024). "This acquired dependency can be exploited, as demonstrated by the hypersensitivity of BRAF-V600E melanoma cells to OXPHOS inhibitors such as 2,4-dinitrophenol, oligomycin A, and the ROS inducer elesclomol." (PMID 39501277, 2024). "UV exposure in melanoma development is highly implicated by mutations in the NRAS and BRAF genes and influenced by the amount of eumelanin produced in the skin." (PMID 38534742, 2024). "Our results are in line with findings in BRAF‐V600E positive melanoma patients, where resistance against the TKI vemurafenib is mediated by the generation of a truncated BRAF splice variant (p61BRAF[V600E])." (PMID 38104968, 2024). "In a Phase I/II trial for advanced BRAF‐mutant melanoma, the regimen of HCQ+dabrafenib+trametinib has demonstrated high ORR and safety." (PMID 39073010, 2024).
melanoma (continued). "We have previously shown that the MEK/ERK kinase, BRAF supports thrombin-induced permeability of human umbilical vein endothelial cells (HUVECs) and in vitro transmigration of A375 melanoma cells through the HUVEC monolayer." (PMID 39457016, 2024). "A combination of these studies suggests a potential MBM prevention benefit using BRAF inhibitor therapeutics for BRAF-mutant melanoma patients." (PMID 38893253, 2024). "Secondly, additional studies are needed to compare the effectiveness of RC48 as a standalone treatment in BRAF-mutant and wild-type melanoma." (PMID 38594618, 2024). "Increase in the efficacy of BRAF inhibitors; counteraction of collagen remodeling; delay in melanoma recurrence." (PMID 39594665, 2024). "Unfortunately, immunotherapies or BRAF/MEK‐based targeted therapies are only effective for a subset of melanoma patients." (PMID 38303608, 2024). "Here, we describe a novel forward genetics screen utilizing the SB mutagenesis system in vivo to monitor the genetic complexity of melanoma xenografts evolving in response to BRAF inhibition." (PMID 38213996, 2024). "BRAF mutations are responsible for the activation of the MAPK/ERK signaling pathway, which is a key factor in cell proliferation and survival of melanoma cells." (PMID 39519055, 2024). "RAF1, also known as CRAF, belongs to the same family as BRAF and participates in the MAPK signaling pathway and is associated with various cancers including melanoma." (PMID 38470950, 2024). "By addressing the neoantigen diversity of BRAF-mutant melanoma, lifileucel shows substantial promise as an option for tailoring immunotherapeutic treatments for individual patients." (PMID 39336897, 2024). "In BRAF V600 mutant melanoma cell lines and tumours, preexisting genomic alterations and factors endogenously secreted by stromal and tumour cells explain primary resistance to BRAF inhibition." (PMID 38333370, 2024). "Our most significant finding is that for BRAF-mutant advanced melanoma patients, first-line immunotherapy provides a better treatment outcome than first-line targeted therapy." (PMID 38473384, 2024). "Lifileucel has demonstrated improved response rates in patients with advanced or unresectable melanoma who have progressed following treatment with immune checkpoint inhibitors and, when applicable, BRAF/MEK inhibitors." (PMID 39336897, 2024). "The combination with DSF seemed to prevent BRAF WT melanoma cells from developing secondary resistance to MEKi." (PMID 38263136, 2024). "Along with the major breakthrough in melanoma treatment with the use of selective BRAF inhibitors, after ~6 months of the median duration, resistance to therapy began to develop." (PMID 38410760, 2024). "For the analysis, we focused on agents targeting EGFR and BRAF that are used in lung adenocarcinomas and melanomas (LUAD and SKCM), respectively." (PMID 39160568, 2024). "The TROCOTEL trial, a multicenter, open-label, single-arm, phase II study, involved a cohort of BRAFV600-mutant melanomas and a BRAF-WT cohort; both groups of patients had melanomas with CNS metastases." (PMID 39727691, 2024). "This switch significantly decreases sensitivity to BRAF inhibitors, leading to therapy resistance and highlighting the complexity of phenotypic plasticity in melanoma." (PMID 39200315, 2024). "The addition of an MEK inhibitor to a BRAF inhibitor has been shown, in patients with melanoma, to limit the paradoxical activation of the ERK pathway and subsequent skin cell proliferation." (PMID 39255538, 2024). "In melanoma, dysregulation of MAPK signaling, often through mutations in upstream effectors like BRAF, leads to unchecked tumor growth and resistance to therapy." (PMID 39835132, 2024). "UV-induced mutations in the BRAF and NRAS genes are also significant risk factors in melanoma development." (PMID 38534742, 2024). "The combination of BRAF and MEK inhibitors (e.g., dabrafenib and trametinib) is now a standard regimen for BRAF‐mutant melanoma." (PMID 39184861, 2024).
melanoma (continued). "More than 50% of melanomas carry mutations in the mitogen-activated protein kinase (MAPK) pathway, with oncogenic alterations in BRAF and NRAS being the most prevalent." (PMID 38942020, 2024). "In BRAFV600-mutant melanoma patients, responses cannot solely be attributed to BRAF/MEKi rechallenge." (PMID 39682270, 2024). "Selecting the first-line treatment for those with advanced-stage BRAF-mutant melanoma has posed challenges." (PMID 39582535, 2024). "MUH viability assays and colony formation assays were performed to study the effects of ENOX2 and BRAF inhibition on melanoma cell lines in vitro." (PMID 39519404, 2024). "In metastatic melanoma in general, but particularly in BRAF wild-type melanoma, the approved immunotherapies anti-PD1, anti-CTLA-4 and, since 2022, anti-LAG3 are being used." (PMID 38263136, 2024). "For patients with BRAFV600 mutant melanoma, BRAF and MEK inhibitors offer likewise excellent treatment options." (PMID 38238578, 2024). "On the other hand, although CTHRC1 was positively correlated with the BRAF(V600E) mutation in melanoma, CTHRC1 expression levels were positively associated with the OS rate in melanoma patients, which was the opposite with colon cancer and thyroid cancer." (PMID 39052013, 2024). "Numerous clinical trials have demonstrated a significant improvement in recurrence‐free survival among melanoma patients receiving high‐dose interferon‐α, immune checkpoint inhibitors (pembrolizumab, nivolumab), and BRAF/MEK inhibitors (dabrafenib‐trametinib)." (PMID 38212945, 2024). "While BRAF inhibitors have been approved for the treatment of melanoma, their limited ability to cross the blood-brain barrier restricts their effectiveness against brain metastases." (PMID 39582535, 2024). "For BRAF V600‐mutant melanoma, the clinical outcomes of first‐line BRAF/MEKi, anti‐PD‐1, and Nivo/Ipi therapies were analyzed in 336 Asian patients." (PMID 38358050, 2024). "This is possible thanks to BRAF inhibitors, including the protein kinase inhibitor vemurafenib (Zelboraf), which is used in the treatment of malignant melanoma." (PMID 38674026, 2024). "As such, resistance to BRAF-targeted therapy is one of the best studied topics in the therapeutic resistance of melanomas." (PMID 38672652, 2024). "Patients with melanoma who have received prior BRAF inhibitor therapy, along with melanoma cell lines resistant to BRAF inhibitors, have exhibited increased expression of PD-1 and PD-L1." (PMID 39420203, 2024). "Recent studies pointed to CDKIs as a promising option for melanoma treatment and potential candidates for synergistic therapies in combination with BRAF/MEK inhibitors." (PMID 39598629, 2024). "Patients with BRAF-mutant melanomas received atezolizumab, vemurafenib and cobimetinib, while BRAF-WT received atezolizumab and cobimetinib." (PMID 39727691, 2024). "Morphological differences between dysplastic nevi, melanoma in situ, and BRAF− and BRAF+ melanoma were observed in H&E slides." (PMID 39273022, 2024). "Over the past decade, immune checkpoint inhibitors (ICI) and TT (BRAF/MEK inhibitors) have become the main efficacious systemic therapies for melanoma." (PMID 38265469, 2024). "The eIF4F translation initiation complex has been identified as an essential player in the development of melanoma resistance to clinical drugs targeting BRAF and MEK kinases." (PMID 39436655, 2024). "The Food and Drug Administration (FDA) has approved the use of a combination of ipilimumab and nivolumab for metastatic or incurable BRAF WT melanoma patients." (PMID 39328455, 2024). "Over the past several decades, multiple treatment approaches to managing BRAF-mutant melanoma have been developed, including BRAF inhibitors, BRAF/MEK inhibitor combinations, anti-PD-1 therapy, and anti-CTLA4 therapy." (PMID 39336897, 2024).